INS (insulin)
Diseases named in the same sentence as INS in open-access papers (continued):
Sharing a sentence is not in itself a finding about the gene and the disease.
type 2 diabetes (continued). "Numerous studies have indicated that carriers of the 482Ser allele have been shown to have a significantly higher risk of developing type 2 diabetes, which may be a consequence of the decrease in insulin secretion observed in carriers of this 482Ser variant." (PMID 36558537, 2022). "Furthermore, studies in Japanese patients with type 2 diabetes linked the defect in hepatic insulin clearance to increased degree of hepatic steatosis rather than to visceral adiposity per se." (PMID 36009446, 2022). "Most recently, there has been a shift in focus towards recognising sub-groups of individuals with glucose intolerance ranging from pre-diabetes to overt type 2 diabetes with their respective risk of developing complications, based on their beta-cell function and insulin sensitivity." (PMID 34561756, 2022). "In those with type 2 diabetes, the catabolic effect of insulin deficiency, coupled with intra‐myocellular lipid accumulation, means that insulin is unable to reduce muscle protein breakdown in the fed state, ultimately creating a negative muscle protein balance." (PMID 35426174, 2022). "South Asians develop type 2 diabetes at younger ages, more rapidly and with lower BMI, so may be more sensitive to weight loss, with physiological differences in insulin resistance, body composition and fat oxidation." (PMID 34796367, 2022). "We identified associations between offspring BW and reduced paternal type 2 diabetes risk, most likely resulting from the independent effects of common type 2 diabetes susceptibility alleles on fetal growth, as described by the fetal insulin hypothesis." (PMID 35951032, 2022). "Accordingly, it was demonstrated that increased adiposity could induce insulin secretion in obese patients, and the associated deterioration of β-cell function is a determinant of impaired fasting glucose leading to type 2 diabetes." (PMID 35327570, 2022). "Finally, the nonsynonymous SNP rs3816873 in the MTTP gene (iHS = 2.43, P = 0.015) was found to significantly associate with lower levels of insulin, blood pressure, and prevalence of type II diabetes in a European population." (PMID 36026493, 2022). "Insufficient insulin levels caused by reduced insulin secretion from the pancreas lead to Type 1 diabetes (T1D), whereas defective insulin signalling causing inefficient utilization of glucose by muscles leads to Type 2 diabetes (T2D)." (PMID 34984701, 2022). "Similarly, high concentrations of omega-3 and omega-6 PUFAs, carotenoids, hyperbilirubinemia, and indolepropionate have been associated with reduced risk of type 2 diabetes, and indolepropionate has also been associated with increased insulin secretion." (PMID 35050191, 2022). "The few pharmacoeconomic studies showed that rapid-acting insulin analogues in type 2 diabetes could be associated with a favorable balance of costs and effects due to the small effects on the hypoglycemic risk and the possible increase of quality of life." (PMID 35288805, 2022). "We believe the observed associations reflect the inheritance of type 2 diabetes susceptibility variants and the interplay of maternal and fetal glucose metabolism in utero, as described by the fetal insulin hypothesis." (PMID 35951032, 2022). "Early efforts to systemically connect type 2 diabetes loci to pathways initially focused on associations of loci with glycaemic traits and broadly connected loci to ‘hard’ clusters related to beta cell function and insulin action." (PMID 35953726, 2022). "Moreover, insulin is involved in the regulatory processes of immune cells promoting subclinical inflammation, a further independent risk factor for type-2-diabetes." (PMID 33922802, 2021). "UPR activation is attributable to the insulin dysfunction associated with type II diabetes." (PMID 34299638, 2021). "Impaired insulin secretion is one of the main causes of type 2 diabetes." (PMID 34578896, 2021).
type 2 diabetes (continued). "The observed differences in case of type 1 diabetes and cancer versus that between type 2 diabetes and cancer may be attributed to the deficiency of endogenous insulin secretion in the former and the coexistence of hyperglycaemia and hyperinsulinemia." (PMID 34535145, 2021). "Besides, dysregulation in insulin signalling is among the typical and earliest metabolic signs predisposing to the development of type 2 diabetes (T2D)." (PMID 34243726, 2021). "Moreover, murine models of type 2 diabetes have shown that decreased expression of miR-26a was associated with decreased insulin sensitivity in pancreatic β cells." (PMID 34690698, 2021). "Moreover, Mendelian randomization studies showed that individuals carrying ≥17 alleles that raise fasting insulin levels have an increased risk of elevated blood pressure, cardiovascular disease and type 2 diabetes." (PMID 34360563, 2021). "Previous MR studies suggest SHBG lowers the risk of type 2 diabetes and possibly lowers insulin resistance, so insulin might underlie the protective effect of SHBG in IHD." (PMID 34848757, 2021). "The increase in exposure to cortisol, an indicator of HPA axis activation, has been linked to decreased insulin sensitivity, a major risk factor for developing type II diabetes, as well as increased risks of various adverse mental and physical health conditions." (PMID 34886393, 2021). "However, insulin treatment can cause weight gain at the same time, and one of the inducements of type 2 diabetes is obesity, thus, obese type 2 diabetes patients will experience a further increase in obesity after receiving insulin treatment." (PMID 34485124, 2021). "Current hypotheses implicate insulin resistance of the brain as a pathogenic factor in the development of Alzheimer’s disease and other dementias, Parkinson’s disease, type 2 diabetes, obesity, major depression, and traumatic brain injury." (PMID 33810179, 2021). "A poor response to insulin commonly arises with obesity and predisposes to type 2 diabetes (T2D)." (PMID 34336862, 2021). "Moreover, the incidence of AP is higher among type-2 diabetics compared to the normal population and the risk of AP is reduced among insulin-treated diabetic patients." (PMID 34282152, 2021). "Furthermore, high-dosages of exogenic induced insulin associated with an increasing CVD risk in older hospitalized patients with type 2 diabetes in an observational study." (PMID 34746266, 2021). "ADIPOQ could increase insulin sensitivity and its circulating levels have been found inversely associated with the risk of type 2 diabetes." (PMID 34702323, 2021). "IR is a critical component of metabolic syndrome, obesity, and hyperlipidemia and is a risk factor for cardiovascular diseases (CVDs) and type 2 diabetes (T2D), especially when an insulin-resistant individual cannot secrete enough insulin from pancreatic β-cells." (PMID 34298896, 2021). "Long-term insulin treatment can affect PR and RI, which might be associated with vascular rigidity of the retinal artery in patients with type 2 diabetes." (PMID 34283877, 2021). "Additionally, LD accumulation in myocytes is associated with a reduced insulin sensitivity in humans, linking lipid metabolism to type 2 diabetes." (PMID 35822042, 2021). "Indeed, increased butyrate production has been causally linked to improved insulin response after an oral glucose-tolerance test, whereas abnormalities in propionate production were associated with an increased risk of Type-2 Diabetes." (PMID 34288919, 2021). "Furthermore, type 2 diabetes is another risk factor for EC as a high level of insulin is an independent factor for EC." (PMID 34769256, 2021). "In this study involving morbidly obese, insulin-resistant individuals at high risk to develop type 2 diabetes, we demonstrated that a LC/high-protein diet is a feasible alternative to a Med diet with balanced macronutrient composition for weight loss and glucose management." (PMID 33919503, 2021).
type 2 diabetes (continued). "Previously associated alleles at ADCY5 were found to be BW lowering and risk increasing for type 2 diabetes, consistent with the fetal insulin hypothesis." (PMID 33955455, 2021). "Recently, a synthetic FGF21 variant, LY2405319, has been shown to reduce low-density lipoprotein (LDL) cholesterol and triglyceride levels, increase adiponectin levels, improve fasting insulin levels, and induce weight loss in obese patients with type 2 diabetes." (PMID 33588950, 2021). "However, some studies have found that Prevotella can participate in the biosynthesis of branched-chain amino acids, which is an important risk factor for the decreased insulin sensitivity, glucose tolerance, and the occurrence of type 2 diabetes." (PMID 34366839, 2021). "Insulin resistance, a major feature of both the metabolic syndrome and type 2 diabetes has been associated with increased mortality for women with breast cancer, possibly related to the growth-promoting effects of insulin, insulin-like growth factors (IGF), and to hyperglycemia." (PMID 33738261, 2021). "Loss of the cells which secrete insulin, the hormone which controls blood sugar levels, can occur due to the damaging effects of high levels of sugar and fat in the bloodstream, and is a key factor which triggers type 2 diabetes." (PMID 33805674, 2021). "Schrieks et al27 hypothesized that the effect of alcohol on both limiting glucose concentration and increasing insulin concentration after a meal may be associated with improved glucose control and a lower risk for type 2 diabetes." (PMID 34499132, 2021). "However, the insulin application is associated with an increased risk of osteoporosis and brittle fractures in patients with type 2 diabetes." (PMID 34200167, 2021). "Additionally, insulin-resistant normal weight individuals had a higher risk of developing type 2 diabetes when compared with insulin-sensitive obese individuals." (PMID 34616552, 2021). "According to all these studies, it could be stated that current evidence indicates the benefits of polyphenols-enriched diets, particularly with flavonoids, on insulin sensitivity that could translate to a significantly reduced risk to develop type 2 diabetes." (PMID 33923263, 2021). "For the known SNPs associated with type 2 diabetes and glycemic traits (P < 0.01), we examined the overlap between their association with beta-cell glucose sensitivity in our study and the early peak insulin response to an intravenous glucose challenge (IVGTT) as previously reported." (PMID 32944759, 2021). "Furthermore, weight was positively associated with miR-375, while it has been shown that both let-7 and miR-375 regulate insulin exocytosis and are associated with type 2 diabetes." (PMID 36303988, 2021). "Moreover, a Trbl mutant designed to mimic a Trib3 variant associated with type 2 diabetes in humans contributed to insulin-resistant phenotypes in the larval model." (PMID 33672471, 2021). "Islet amyloid deposits may play an important role in the loss of β cells and the progressive decline in insulin secretion characteristic of type 2 diabetes." (PMID 33521358, 2021). "Interestingly, similar associations have been observed for type 2 diabetes in large prospective cohorts possibly reflecting some of the pathogenic disturbances caused by a failure in insulin secretion and signaling." (PMID 33574451, 2021). "The higher perceived appropriateness of insulin might be caused by the efforts of health care providers that are often needed to convince type 2 diabetes patients to start injecting insulin." (PMID 34134649, 2021). "Detection of GADA by ECL assay, given technical advantages over RBA-GADA, identified adult-onset diabetes patients at higher risk of requiring early insulin treatment, as did clinical phenotype, together allowing for more accurate clinical diagnosis and management." (PMID 34272582, 2021).
type 2 diabetes (continued). "Moreover, branched-chain amino acids do not stimulate glucagon secretion but are associated with insulin secretion in type 2 diabetes." (PMID 34382579, 2021). "However, insulin treatment has been reportedly associated with increased mortality in patients with COVID-19 and type 2 diabetes." (PMID 33859617, 2021). "While there is now clear support for the fetal insulin hypothesis, the question remains as to how much of the association between lower birthweight and type 2 diabetes is explained by the genetic associations." (PMID 33569631, 2021). "Furthermore, they are positively correlated with the severity of diabetic retinopathy in patients with type 2 diabetes, indicating the close association between adiponectin levels and the maintenance of insulin sensitivity." (PMID 34641407, 2021). "Consequently, type 2 diabetes is constantly rising, which is characterized by reduction of the insulin-producing β-cell mass, insulin production/secretion, loss of sensitivity to insulin, liver and pancreas steatosis and inflammation." (PMID 34112759, 2021). "Although it is well described that the development of type 2 diabetes is positively associated with body weight, we did not observe a strong correlation between fat mass and glucose and insulin sensitivities in males obtained after multigenerational WD feeding." (PMID 33783350, 2021). "Type 2 diabetes (T2D) is a complex disease with both genetic and environmental risk factors that ultimately manifests when pancreatic β cells are unable to secrete adequate amounts of insulin in response to elevated blood glucose levels." (PMID 34475398, 2021). "Moreover, taurine deficiency is linked to type II diabetes, cardiovascular diseases and obesity while taurine supplementation lowers arterial blood pressure and has positive effects on insulin sensitivity." (PMID 34012512, 2021). "It has been reported to modulate insulin secretion, and it might be associated with type 2 diabetes." (PMID 35046932, 2021). "Horses are susceptible to a condition known as Equine Metabolic Syndrome (EMS), which is somewhat similar to metabolic syndrome and type II diabetes in people, and is characterized by elevated insulin levels and increased susceptibility to other adverse health outcomes." (PMID 33915682, 2021). "In summary, there is now ample evidence to support the idea that variants of certain genes which result in impaired pancreatic beta cell function and reduced insulin secretion contribute to both lower birthweight and higher type 2 diabetes risk in later life when inherited by the fetus." (PMID 33569631, 2021). "Interestingly, studies in humans have shown that ZnT8 loss-of-function mutants are associated with increased insulin secretion capacity and lower risk of developing type 2 diabetes." (PMID 34413780, 2021). "Type 2 diabetes, comprising 90–95% of all diabetics, stems from a relative insulin deficiency as a result of the body becoming increasing resistant to the glucose lowering effects of insulin." (PMID 34458216, 2021). "Potassium voltage-gated KQT-like (KCNQ1) channels play a role in the intestinal secretion of GLP-1 and glucose-dependent insulinotropic polypeptide (GIP), and polymorphisms in the gene coding for these channels have been linked to type 2 diabetes through a role in insulin release." (PMID 33594477, 2021). "While preparing our paper for publication, two separate analyses have suggested that insulin therapy in hospital may be associated with increased mortality in patients with type 2 diabetes." (PMID 34268452, 2021). "Furthermore, as reported in previous literatures, the increased utilization of insulin in patients with type 2 diabetes was usually associated with poor glycemic control in the long run." (PMID 34367063, 2021).
type 2 diabetes (continued). "As insulin released from fetal pancreatic beta cells is a crucial fetal growth factor, it is suggested that genetic variants predisposing to decreased insulin secretion or action cause reduced intrauterine growth and thereby lower birth weight as well as late-onset type 2 diabetes." (PMID 33490284, 2020). "We also found that glucose intolerance, plasma insulin and plasma triglyceride levels in 22-week-old db/db mice were increased in db/db mice compared to db/db mice treated with NaHS, recapitulating the hallmark features of type 2 diabetes." (PMID 32257541, 2020). "Previous studies have also revealed that low-GI diets have the tendency of increasing glycemic control in people who have low tolerance to glucose and type-II diabetes by reducing fasting blood glucose and glycated proteins and also cause insulin sensitivity to improve." (PMID 32843013, 2020). "We have hypothesized that reduction in insulin clearance, particularly in liver, might be one cause of Type 2 diabetes, at least in some individuals." (PMID 33658981, 2020). "Consistent with this notion, Bian and colleagues proposed that ACAD10 variation in Pima Indians may increase susceptibility to type 2 diabetes and that this effect may be mediated by impairment of insulin sensitivity via abnormal lipid oxidation." (PMID 32196924, 2020). "Besides, raised basal insulin secretion under fasting conditions along with deficient stimulated insulin secretion is an important indication of type 2 diabetes." (PMID 32331428, 2020). "The risk allele of KCNQ1 for type 2 diabetes is also associated with impaired insulin secretion, suggesting that the risk allele might confer susceptibility." (PMID 32722593, 2020). "Studies have shown up‐regulation of GDF‐15 in cardiovascular diseases (cardiomyopathies, heart failure, atrial fibrillation, and stroke) and with type 2 diabetes, where higher levels associated with fasting glucose, insulin resistance index, and glycated hemoglobin." (PMID 32762010, 2020). "This is the first randomized clinical trial to demonstrate that a low-energy TDR-based lifestyle intervention safely induces weight loss, reduces insulin requirements, and improves QoL specifically in participants with long-standing type 2 diabetes and obesity receiving IT." (PMID 32049634, 2020). "In addition, WBC count was reported to be associated with adiponectin, which is highly linked to type 2 diabetes, as it mediates insulin sensitivity." (PMID 32346379, 2020). "In an outpatient cohort, over 90% of patients with type 2 diabetes and failure of metformin monotherapy reached their individual HbA1c goal with additional basal insulin at bedtime over several years in association with a reduction of bodyweight as well and without any event of severe hypoglycaemia." (PMID 32316649, 2020). "These pollutants may also induce type 2 diabetes, which is associated with fat storage and obesity, perhaps as a consequence of tissue damage (particularly to insulin-secreting β-cells) and consequent pancreatic dysfunction." (PMID 32604970, 2020). "It is well-documented that palmitic acid is associated with obesity, with decreased insulin sensitivity that could increase risk of type 2 diabetes and higher cardiovascular disease risk through increased level of blood cholesterol much more of other SFAs." (PMID 33613624, 2020). "In addition, the mutation R197H has > 50% decreased binding affinity with the human insulin promoter sequence and is associated with type 2 diabetes." (PMID 33076817, 2020). "Early studies have shown that GNPNAT1 deficiency may reduce insulin secretion associated with type 2 diabetes." (PMID 33178836, 2020). "Additionally, in a large general practice cohort in the United Kingdom including patients with insulin-treated type 2 diabetes, a regression in albuminuria associated with a significant reduction in all-cause mortality was observed." (PMID 31954408, 2020).